RNA5SP536 (RNA, 5S ribosomal pseudogene 536)
Gene: Ribosomal RNA gene on chromosome 1 (146,539,541 to 146,539,663, reverse strand). Ensembl gene ENSG00000274408.
Homologues: Orthologues: chimpanzee 5S_rRNA (97% identical), guinea pig 5S_rRNA (60% identical). Paralogues in human: RNA5S1 (64% identical), RNA5S10 (64% identical), RNA5S11 (64% identical), RNA5S12 (64% identical), RNA5S13 (64% identical), RNA5S14 (64% identical), RNA5S15 (64% identical), RNA5S16 (64% identical), RNA5S17 (64% identical), RNA5S2 (64% identical), RNA5S3 (64% identical), RNA5S4 (64% identical), and 26 more.